FAS (Fas cell surface death receptor)
Diseases named in the same sentence as FAS in open-access papers (continued):
Sharing a sentence is not in itself a finding about the gene and the disease.
lymphopenia (20 papers, 2011 to 2025). Reduction in the number of lymphocytes. "It was previously suggested that the relative lymphopenia in PD could be caused by FAS-mediated apoptosis related to CD25." (PMID 23054369, 2012). "Treg lymphocytes have higher proliferation levels than conventional T cells in response to lymphopenia after HSCT, but they are also more susceptible to apoptosis mediated by FAS, resulting in a relative deficiency of Tregs in extensive cGVHD." (PMID 35486633, 2022). "Herein, we report on a case of disseminated varicella zoster infection after post-partum vaccination in a patient found to have CD4 lymphopenia and eventually diagnosed with ALPS caused by a novel germline missense mutation in FAS death-domain." (PMID 31191551, 2019). "The decrease in CD31 in combination with increased FAS, contributes to apoptosis and the subsequent relative lymphopenia." (PMID 23054369, 2012). "In line with this, we observed elevated expression of pro‐apoptotic molecules (e.g. CASP3, FAS, CASP8, IRF1 etc.)in coinfected patients with severe disease, suggesting that cell apoptosis may be associated with the lymphopenia observed in severe coinfection." (PMID 41163794, 2025). "ALPS-FAS has not been previously associated with CD4 lymphopenia and such finding in our index patient was unexpected and counterintuitive in a disorder of FAS-mediated apoptosis, which is usually associated with lymphocytosis and lymphoproliferation." (PMID 31191551, 2019). "Further analysis revealed activation of multiple cell apoptosis pathways (e.g., granzyme/perforin-, FAS- and TNF-induced apoptosis) may be responsible for lymphopenia." (PMID 37848421, 2023). "Interestingly, we did not detect changes in the expression of genes that play a role in lymphocyte apoptosis such as FAS, caspase, and TRAIL despite the lymphopenia we observed in vivo." (PMID 29123522, 2017). "Thus, the higher expression of FAS and FASL on the surface of T lymphocytes, induced by SARS-CoV-2 infection, may contribute to triggering apoptosis of these cells, leading to the development of lymphopenia." (PMID 39859379, 2025).
Sepsis (16 papers, 2013 to 2025). Sepsis is defined as life-threatening organ dysfunction caused by a dysregulated host response to infection. "Studies in murine CLP-sepsis by other groups have also demonstrated that inhibition of apoptosis through treatment with siRNA against caspases or FAS-associated death domain rescues septic EC dysfunction, including reducing septic hyper-permeability." (PMID 30116240, 2018). "Conditional global FAS knockout mice die from neutropenic sepsis due to disrupted membrane phospholipid composition in FAS KO neutrophils." (PMID 31616403, 2019). "Low expression of ARHGEF10L in CD14 + monocytes is associated with increased death from sepsis, and the list included genes related to anti-bacterial activity (LCN2), regulation of TLR4 responses (SLC15A3), LPS sensitivity and autophagy (RUBCNL and SLC8A1) and apoptosis (FAS, TNFRSF21, TNFRSF8)." (PMID 39730996, 2024). "Whether apoptosis primarily has protective or harmful consequences during systemic inflammation is still unknown but CASP3, BCL2L1, FAS, and BID are all reported to be differentially expressed in human patients suffering from different stages of sepsis." (PMID 26076814, 2015).
pancreatic cancer (15 papers, 2003 to 2025). "Lipidomics studies are so important because altered lipid metabolism has been observed for drug resistance; e.g., increased de novo lipogenesis mediated by FAS facilitated gemcitabine resistance in pancreatic cancer." (PMID 38674093, 2024). "Many studies have reported that FAS expression is aberrant in various pancreatic tumours while FASLG is seen in both normal pancreatic cells and pancreatic neoplasia." (PMID 32606315, 2020). "As CHST11 is a key enzyme for glycosaminoglycan sulfation, these results suggest CHST11+ naive T cells in pancreatic cancer may have "Th2 differentiation tendency" and promote T cell exhaustion by enhancing apoptosis sensitivity via the FAS/FASLG pathway." (PMID 41346619, 2025). "However, a high level of FAS mRNA expression indicated poorer OS in pancreatic cancer (HR: 1.33 [1.06, 1.66]; p=0.01) and acute myeloid leukemia (AML) (HR: 1.57 [1.02, 2.41], p=0.04)." (PMID 31942177, 2020). "Furthermore, ectopic expression of TRAF2 in the FASL-sensitive pancreatic cancer cell line Colo357 confers resistance towards FAS-mediated apoptosis, arguing for a pivotal role of TRAF2 in mediating FAS resistance of pancreatic cancer cells." (PMID 18652674, 2008).
diabetes (14 papers, 2017 to 2025). "The mRNA expressions of SREBP-1c and FAS were lower in the liraglutide group than that in the diabetes group." (PMID 29213335, 2017). "In addition, we identify several proteins biomarkers to be associated with glycaemic deterioration in diabetes, including NogoR (RTN4), IL-18Ra, CRELD1, ENPP7 and FAS." (PMID 37137910, 2023). "Moreover, we noted that FAS, but not ACC1, was increased in both type 1 (STZ induced) and type 2 (db/db) diabetes model, indicating that lipogenic enzyme FAS might be specifically induced by hyperglycemia." (PMID 33186123, 2020). "There were dramatic downregulations of FAS mRNA and SREBP-1c in the liraglutide group compared with the diabetes group." (PMID 29213335, 2017). "FAS and SREBP-1c are two important adipogenesis regulators that are particularly important for the occurrence and progression of metabolic diseases such as diabetes and MASLD." (PMID 40138287, 2025). "Given the well-established molecular link between Sirt1 and PPARG signaling and the detrimental role played by PPARG in the context of MCM, we examined PPARG and PPARG-dependent genes LPL, PLIN, CD36, FAS and PPARA in cardiac specimens from diabetics and controls." (PMID 37957697, 2023). "In contrast to ENPP7, we find that CRP, FAS, and GDF15 are the most studied targets for diabetes." (PMID 37590326, 2023). "In the non-obese diabetic (NOD) mouse model of autoimmune diabetes, blocking FAS signalling, and thus FAS-mediated apoptosis, in beta cells did not protect NOD mice from diabetes, indicating FAS-mediated beta-cell death is not important in diabetes pathogenesis." (PMID 31552143, 2019).
Insulin resistance (14 papers, 2014 to 2025). Increased resistance towards insulin, that is, diminished effectiveness of insulin in reducing blood glucose levels. "As hepatic triglyceride storage is associated with triglyceride synthesis and insulin resistance, the mRNA expression of FAS and peroxisome proliferator-activated receptors (PPAR)-γ was determined." (PMID 35804768, 2022). "FAS is key enzyme in de novo lipogenesis that produces first fatty acids, increases insulin resistance, and converts malonyl-CoA to palmitate." (PMID 34441691, 2021). "When insulin resistance existing, the body weight was increasing, and the level of FAS in adipose tissue was up-regulated." (PMID 31908653, 2020). "Increased concentration of FFA induces insulin resistance and elevates the expression of the hepatic lipogenic genes, including SREBP1c and FAS in the liver." (PMID 30558262, 2018). "Metformin and OA induced AMPK and ACC activation, reduced the downregulation of lipogenic enzymes, such as FAS, and increased pyruvate kinase activity, thus improving insulin resistance." (PMID 25789330, 2015). "Studies have shown that the inhibition of FAS might be beneficial for insulin resistance." (PMID 31908653, 2020). "AMPK activation downregulates SREBP-1c expression and subsequently inhibits the expression of lipogenic genes such as ACC, FAS, SCD1, and HMGCR in insulin-resistant mice." (PMID 41194880, 2025). "The Gal OSL nanocarrier has demonstrated efficacy in mitigating liver lipid accumulation, insulin resistance, and triglyceride (TG) accumulation through the regulation of the AMPK/SIRT/FAS/SREBP1c signaling pathway." (PMID 37569884, 2023). "The results of this study showed that AFG effectively reduced the expression of SREBP-1, FAS, and MCP-1 genes in DM mice, inhibited inflammatory reactions, reduced fat accumulation, and improved insulin resistance." (PMID 32714403, 2020).
cervical carcinoma (13 papers, 2008 to 2024). A carcinoma arising from either the exocervical squamous epithelium or the endocervical glandular epithelium. "The aim of the study was to evaluate the association of two SNPs of EVER1/2 genes’ region (rs2290907, rs16970849) and the FAS-670 polymorphism with the susceptibility to precancerous lesions and cervical cancer in a Greek population." (PMID 27899077, 2016). "The aim of our study was to evaluate the association of two SNPs of EVER1/2 genes’ region (rs2290907, rs16970849) as well as the FAS-670 polymorphism with the susceptibility to precancerous lesions and cervical cancer in a Greek population." (PMID 27899077, 2016). "The aim of our study was to evaluate the potential contribution of certain EVER1/2 and FAS polymorphisms to the susceptibility for cervical cancer." (PMID 27899077, 2016). "The FAS-670 polymorphism was included in the present study in order to enhance the already existing and quite contradictory data concerning its association with cervical cancer." (PMID 27899077, 2016). "Therefore, the expression of the FAS/FASL genes may represent an important element in the susceptibility for the development of cervical cancer." (PMID 27899077, 2016). "We detected previously unreported recurrent mutations in cervical cancer in GPX1, MSN, FAS, KRT8, and SPRED3, all genes known to modulate tumorigenic processes." (PMID 34620846, 2021). "The findings of our study agree with the conclusions of these two recently published meta-analyses, validating the absence of association between the FAS-670 promoter polymorphism and susceptibility to persistent precancerous lesions and development of cervical cancer in the Greek female population." (PMID 27899077, 2016). "Thus, the present data indicates that BV could be effective for treatment of cervical cancer through up-regulation of FAS, DR3 and DR6, but inactivation of NF-κB." (PMID 25730901, 2015). "However, even without being correlated with susceptibility to cervical cancer, some genotypes of the FAS/FASL polymorphisms could be related to the risk of lymph node metastasis of cervical cancer." (PMID 27899077, 2016). "In conclusion, our results that natural toxin BV could be useful as an anti-cancer agent through activation of extrinsic apoptosis pathway by overexpression of FAS, DR3 and DR6, and by inactivation of NF-κB for treatment of cervical cancer cells." (PMID 25730901, 2015). "Although cervical cancer cells can induce the tumor-specific cytotoxic T lymphocytes (CTLs) apoptosis, the fact that an anti-CD95 antibody could block apoptosis, indicates that tumor cells induce apoptosis of CTLs through CD95-CD95 ligand (FAS/FASL) interaction." (PMID 27899077, 2016).
HIV-1 infection (13 papers, 2011 to 2025). The type species of lentivirus and the etiologic agent of acquired immunodeficiency syndrome (AIDS). "In HIV-1 infection, the FAS rs1800682 (A/G) and FAS rs2234767 (G/A) polymorphisms were associated with the apoptosis of CD4+ T lymphocytes and disease progression in people living with HIV-1." (PMID 39859379, 2025). "Functional loss of γδ T cells as a result of upregulation of the FAS and FAS ligand has been correlated with disease progression in M. tuberculosis and HIV-1 infection." (PMID 31111075, 2019). "Polymorphisms in the FAS and FASL genes suggested that the FAS-670 polymorphism might be associated with apoptosis of T CD4+ lymphocytes after HIV-1 infection." (PMID 34067165, 2021). "The FAS rs1800682 (A/G) and FASL rs5030772 (A/G) polymorphisms have been associated with higher proviral load and the development of human T-cell lymphotropic virus type 1 (HTLV-1)-associated and with the progression of human immunodeficiency virus type 1 (HIV-1) infection and disease development." (PMID 39859379, 2025). "Because HIV-1 infection also sensitizes CD4 T cells to extrinsic apoptosis induced by FAS ligation, we also questioned whether bryostatin-1 would inhibit FAS-mediated apoptosis in HIV-infected cells." (PMID 33075109, 2020). "The VL started a unique line of investigation looking for gene polymorphisms of the immune and inflammatory responses which could be biomarkers influencing the progression of HIV-1 infection, including mannose-binding lectin (MBL), IL6, IFNγ, IL-8, IL-10, TGFβ and FAS/FASL genes." (PMID 34067165, 2021).
Fulminant hepatitis (10 papers, 2006 to 2024). Acute hepatitis complicated by acute liver failure with hepatic encephalopathy occurring less than 8 weeks after the onset of jaundice. "Fulminant hepatitis causes acute, severe liver injury as a result of massive hepatocyte apoptosis and necrosis induced by death receptor signaling, involving FAS, TNF receptor, and TNFSNF10b, leading to lethality." (PMID 32238456, 2020). "Utaipan T emphasised the efficacy of ursodeoxycholanoyl lysophosphatidyl ethanolamide in averting CD95 / FAS-induced fulminant hepatitis." (PMID 39390593, 2024). "To investigate the sensitivity of WT and MET D3174N mouse liver tissues to apoptosis, we focused on FAS-induced fulminant hepatitis, a condition in which HGF/SF production is reported to promote hepatocyte survival." (PMID 32091387, 2020). "However, an unexpected major obstacle appeared, namely, the FAS agonist antibodies induced the death of hepatocytes leading to fulminant hepatitis and the death of treated animals." (PMID 39068622, 2024).
hyperlipidemia (10 papers, 2011 to 2023). "Therefore, it is suggested that 6-gingerol reduces the extent of lipogenesis by downregulating lipogenic transcription factors, such as SREBP-1, PPARγ, and C/EBPα, leading to a reduced expression of FAS, which, in turn, attenuates hyperlipidemia associated with adiposity." (PMID 37571394, 2023). "ATF4 overexpression induces early onset of hyperlipidemia in zebrafish, while hepatic lipogenesis was diminished in fructose-fed ATF4-deficient mice with impacts on downregulation of PPAR-γ, SREBP-1, ACC and FAS." (PMID 33308192, 2020). "Furthermore, the mRNA expression of SIRT1 and FOXO1 slightly increased, while FAS was subsequently decreased in the perirenal adipose tissue, which demonstrated a reduction in fatty acid synthesis and therefore reduced the development of hyperlipidemia." (PMID 37835191, 2023). "The trends in the protein levels of FAS, LXR, SREBP1c, and PPARα were similar to those found in the mRNA expression, which is in accordance with a prior finding about the prevention of a probiotic-fermented rice buckwheat on HFD-induced hyperlipidemia in mice." (PMID 36230104, 2022). "However, significantly decreasing of liver lipogenic genes FAS, ACC, SREBP-1c, and SCD-1 were observed when treated with ICAC in hyperlipidemia mice." (PMID 35959429, 2022). "Interestingly, we found that ACC1 and FAS were increased by STZ treatment, while DGAT2 was upregulated in HFD-treated mice, indicating that hyperglycemia and hyperlipidemia might promote lipogenesis by activating distinct lipogenic genes, respectively." (PMID 33186123, 2020).
bladder cancer (9 papers, 2012 to 2024). "Bladder cancer is associated with mutations of the FAS death receptor in almost 30% of cases, most often missense mutations in the region encoding the death domain responsible for the transduction of apoptotic signals." (PMID 38791085, 2024). "In bladder cancer, a downregulation of FAS was noted in cancer cells compared to the surrounding normal urothelium." (PMID 38791085, 2024). "Amentoflavone markedly inhibits TSGH-8301 bladder cancer cell activity via the induction of mitochondria-dependent intrinsic apoptosis and Fas cell surface death receptor (FAS)/FAS ligand (FASL)-dependent extrinsic apoptosis." (PMID 33996570, 2021). "An immunohistochemical study of FAS and FASL, which included 40 UBC of different stages, indicated a significant reduction in the expression of FAS and increased expression of FASL in bladder cancer tissue." (PMID 38791085, 2024). "In bladder cancer, AF induces FAS/FASL‐dependent extrinsic apoptosis through increasing pro‐apoptotic protein levels of FAS and FASL." (PMID 38842135, 2024). "In bladder cancer, AMF induces FAS/FASL-dependent extrinsic apoptosis through increasing pro-apoptotic protein levels of FAS and FASL." (PMID 35002708, 2021). "Promising pathways for early detection, diagnosis, and prognosis of bladder cancer are provided by these biomarkers, which include the UBC® Rapid test, UBC ELISA kit, Xpert® Bladder Cancer Monitor, BC UroMark, TaqMan® Arrays, Soluble FAS (sFAS), Bladder tumor fibronectin (BTF), and IGF2 and MAGE-A3." (PMID 39678505, 2024). "Moreover, β-lapachone also inhibits FAS and FASL in a dose-dependent manner in bladder cancer." (PMID 33996570, 2021).
Hepatitis (9 papers, 2011 to 2025). Inflammation of the liver. "The role of the FAS gene in AIH is supported by the results from animal models; Fas-deficient mice are less sensitive to Concanavalin A-induced hepatitis, an AIH animal model." (PMID 33509297, 2021). "After 18 weeks, HFD mice developed NASH like features with severe steato-hepatitis and fibrosis, increased hepatic content of triacylglycerol and cholesterol and expression of SREPB1c, FAS, ApoC2, PPARα and γ, α-SMA, α1 collagen and MCP1 mRNAs." (PMID 28202906, 2017).
liver cancer (9 papers, 2015 to 2024). An epithelial or non-epithelial malignant neoplasm that arises from the liver. "It is known that FAS, one of the target genes, that participates in fatty acid metabolism and lipogenesis, is downregulated by Cur and its intracellular protein activity is also inhibited, leading to the death of liver cancer cells." (PMID 27736939, 2016). "Specifically, dehydrocrenatidine significantly increased the expression of extrinsic pathway components (FAS, DR5, FADD, and TRADD) as well as intrinsic pathway components (Bax and Bim L/S) in liver cancer cells." (PMID 35455398, 2022).
malaria (9 papers, 2011 to 2024). Malaria is a serious and sometimes fatal disease caused by a parasite that commonly infects a certain type of mosquito which feeds on humans. "The INS/INS genotype of rs10562972 (FAS) was identified as a risk factor for malaria caused by P. vivax when compared to P. falciparum." (PMID 37794476, 2023). "Collectively, our results show that the variant c.−436C>A in the promoter region of the FAS gene was associated with protection from severe malaria in Ghanaian children." (PMID 21625619, 2011). "We found that a single nucleotide variant in the FAS promoter was associated with a 29%–reduced risk of developing severe malaria." (PMID 21625619, 2011). "Notably, complement genes (C1QA, C1QB, C1QC), apoptotic genes (PDL1, PDL2, APOL1, APOL2, FAS), inflammatory caspases (CASP1, CASP5), TLR pathway genes (TLR1, TLR4, TLR5, TLR8), cytokines (IL6, IL10), and granzyme (GZMB) were among the genes upregulated during symptomatic malaria." (PMID 39161730, 2024).